SERPINA7 (serpin family A member 7)
Description:
Major thyroid hormone transport protein in serum.
Synonyms: TBG; TBGQTL
Tractability: Small molecule: a structure with a bound ligand is known; it has a high-quality binding pocket. Antibody: UniProt places it where antibodies can reach, with medium confidence; UniProt predicts a signal peptide or a membrane-spanning region; its Gene Ontology location is reachable by antibodies, with medium confidence. PROTAC: its protein half-life has been measured.
Target class: Secreted protein
Gene: Protein-coding gene on chromosome X (106,032,425 to 106,038,778, reverse strand). Ensembl gene ENSG00000123561.
Subcellular location: Secreted
Gene Ontology:
Molecular function: serine-type endopeptidase inhibitor activity
Biological process: thyroid hormone transport
Cellular component: extracellular exosome; extracellular region
Homologues: Orthologues: chimpanzee SERPINA7 (99% identical), macaque SERPINA7 (95% identical), rabbit SERPINA7 (83% identical), pig SERPINA7 (82% identical), dog SERPINA7 (82% identical), rat Serpina7 (77% identical), mouse Serpina7 (76% identical), guinea pig SERPINA7 (73% identical). Paralogues in human: SERPINA9 (50% identical), SERPINA4 (43% identical), SERPINA11 (42% identical), SERPINA3 (42% identical), SERPINA1 (40% identical), SERPINA6 (39% identical), SERPINA5 (36% identical), SERPINA12 (34% identical), SERPINA10 (31% identical), SERPINB10 (30% identical), SERPINB4 (29% identical), SERPINB3 (29% identical), and 24 more.
Diseases named in the same sentence as SERPINA7 in open-access papers:
SERPINA7 is named in the same sentence as 60 diseases in open-access papers, as found by Europe PMC text mining. Sharing a sentence is not in itself a finding about the gene and the disease. The quoted sentences say what the papers report.
hypothyroidism (12 papers, 2017 to 2025). Abnormally low levels of thyroid hormone. "While the expression of TTR was not impacted by MMI‐induced fetal hypothyroidism, there was a significant downregulation in the expression of SERPINA7 in the MMI fetuses at GDs 66 and 76 relative to the equivalent age‐matched CONs (p = 0.011 and p < 0.001, respectively)." (PMID 40939099, 2025). "SERPINA7 variants caused TBG deficiency which does not require treatment, but the decreased thyroxine may be misdiagnosed as hypothyroidism." (PMID 33554479, 2021).
COVID-19 (3 papers, 2021 to 2024). A disease caused by infection with severe acute respiratory syndrome coronavirus 2. "Here, we selected five significant proteins for COVID-19 non-severe versus severe comparison: heparin cofactor 2 (SERPIND1), thyroxine-binding globulin (SERPINA7), angiotensinogen (AGT), carbonic anhydrase-1 (CA1), and carbonic anhydrase-2 (CA2) for docking study." (PMID 33995121, 2021).
liver steatosis (3 papers, 2010 to 2025). "In thymectomized mice, we observed an upregulation of novel genes that have demonstrated to either be causal (Mogat1, Pklr) or associated with liver steatosis (Serpina7, and Hcn3)." (PMID 41034932, 2025).
Obesity (3 papers, 2019 to 2023). Accumulation of substantial excess body fat. "By comparing regulators that were identified for lean, obese, and merged islet expression data, Cck, C1ql3, Serpina7, Creld2, Svop, Smoc1, Tgfβ3, and Serpini1 were identified to affect islet function in obesity." (PMID 31300714, 2019).
steatosis (3 papers, 2018 to 2025). Increased lipid within the cytoplasm of cells. "Thymectomy also resulted in upregulation of Serpina7 and Hcn3 which are highly upregulated in various models and tissues of diet induced steatosis, however the exact role of these genes in hepatic dysfunction is still unclear." (PMID 41034932, 2025).
Graves disease (2 papers, 2018 to 2024). Graves' disease is an autoimmune disorder that leads to overactivity of the thyroid gland (hyperthyroidism).It is caused by an abnormal immune system response that causes the thyroid gland to produce too much thyroid hormones. "Investigation of a male patient with low serum TSH and TT4, but raised FT4 concentrations and thyroid stimulating immunoglobulins, identified hemizygosity for a pathogenic mutation in the TBG (SERPINA7) gene, hence signifying coincident TBG deficiency and Graves disease." (PMID 37988295, 2024).
Hyperglycemia (2 papers, 2020 to 2024). An increased concentration of glucose in the blood. "The most striking change was however revealed by the drastic reduction in the expression of Aldh1a3 and Serpina7 in SHD-STZ + Tx islets, thereby evidencing the major involvement of hyperglycemia in β-cell dedifferentiation." (PMID 32999405, 2020).
clear cell carcinoma (1 paper, 2015). "Other genes significantly associated with EOC histological subtypes (p<0.05) included the UGT1A (endometrioid), SLC25A45 (mucinous), SLC39A11 (low malignant potential), and SERPINA7 (clear cell carcinoma)." (PMID 26091520, 2015).
emphysema (1 paper, 2014). "Higher SERPINA7 levels were also associated with more radiologic emphysema." (PMID 25306249, 2014). "Cadherin 13 (CDH13) and thyroxin-binding globulin (SERPINA7) were positively correlated with emphysema severity (p < 0.001 for all comparisons)." (PMID 25306249, 2014). "Other biomarkers such as CHD1, CDH13 and SERPINA7 may also have a role in evaluating emphysema (especially milder emphysema), although require confirmation in other cohorts." (PMID 25306249, 2014). "The study confirms a previously identified association between radiologic emphysema and sRAGE, builds on data suggesting a role for ICAM1 as a biomarker, in addition to discovering previously not identified biomarkers associated with emphysema such as CCL20, cadherin 1, cadherin 13 and SERPINA7." (PMID 25306249, 2014). "Other biomarkers that were associated with emphysema include CDH1, CDH 13 and SERPINA7, but were not available for validation in the TESRA study." (PMID 25306249, 2014).
osteosarcoma (1 paper, 2023). A usually aggressive malignant bone-forming mesenchymal neoplasm, predominantly affecting adolescents and young adults. "In patients with osteosarcoma, SERPINH1 and SERPINA7 were found to be two independent prognostic indicators by univariate Cox regression analysis on the serpin superfamily." (PMID 37091161, 2023).
pancreatic cancer (1 paper, 2023). "For example, thyroxine-binding globulin (SERPINA7) which binds thyroid hormones in the blood, and thyroid hormones triiodothyronine (T3) and thyroxine (T4) which have a promoting and inhibitory action on the growth and invasion of pancreatic cancer cells." (PMID 37759310, 2023).
pulmonary embolism (1 paper, 2018). The obstruction of the pulmonary artery or one of its branches by an embolus, sometimes associated with infarction of the lung. "The carrier frequency of rs1804495 on SERPINA7 was significantly higher in cases than in control groups (PControl < 0.001, PEAS = 0.018, and PT1GP = 0.001), and nine patients carried this allele including two with pulmonary embolism." (PMID 29368655, 2018).
tumor (5 papers, 2012 to 2025). "These include hormone transport, as observed with cortisol binding globulin (CBG) (SERPINA6) and thyroxine binding globulin (TBG) (SERPINA7), molecular chaperoning (SERPINH7) or tumour suppression (SERPINB5)." (PMID 34198546, 2021).
cancer (1 paper, 2015). A tumor composed of atypical neoplastic, often pleomorphic cells that invade other tissues. "The specific role of SERPINA7 in cancer etiology has not been established; however, thyroid hormones may support cancer growth." (PMID 26091520, 2015).
SERPINA7 also shares sentences with these, for which no sentence is quoted: nephrotic syndrome (5 papers); liver disease (4); hyperestrogenism (3); infection (3); Insulin resistance (3); liver fibrosis (3); thyroid (3); amyloidosis (2); hyperthyroidism (2); Primary hypothyroidism (2); schizophrenia (2); thyroid cancer (2); acute intermittent porphyria (1); acute myocardial infarction (1); Adrenal insufficiency (1); Alzheimer disease (1); anemia (1); atherosclerosis (1); cardiovascular diseases (1); Chronic colitis (1); Cirrhosis (1); congenital central hypothyroidism (1); congenital hypothyroidism (1); diabetes (1); fetal growth restriction (1); focal segmental glomerulosclerosis (1); glaucoma (1); glomerular disease (1); goiter (1); hepatoblastoma (1).
A further 16 diseases each share a sentence with SERPINA7 in 1 paper.